FGF21 (fibroblast growth factor 21)
Diseases named in the same sentence as FGF21 in open-access papers (continued):
Sharing a sentence is not in itself a finding about the gene and the disease.
periodontitis (2 papers, 2020 to 2022). An acute or chronic inflammatory process that affects the tissues that surround and support the teeth. "The elevation of serum FGF21 might be a potential biomarker for MetS patients who have risk of generalized periodontitis." (PMID 36474191, 2022). "Conversely, the other two studies validating serum FGF21 in diabetic patients with periodontitis presented the contradictory results." (PMID 36474191, 2022). "This is the first study reporting the alterations of serum FGF21 levels in MetS patients with periodontitis." (PMID 36474191, 2022). "An alteration of FGF21 is possibly affected by periodontitis." (PMID 36474191, 2022). "The findings suggested that the elevation of FGF21 in GCF might act as a protective mechanism to oppose periodontal inflammation in diabetic patients with periodontitis." (PMID 36474191, 2022). "FGF21 is one of protein molecules that potentially involves the inflammatory and immunity response which is a fundamental process in pathogenesis of MetS and periodontitis." (PMID 36474191, 2022). "Therefore, the further studies about relationship between FGF21 and periodontitis is still needed to be clarified." (PMID 36474191, 2022). "Although the studies report contradictory findings, the expression of serum FGF21 in MetS patients might be related to periodontitis-induced inflammation." (PMID 36474191, 2022). "It was thus possible that the elevation of serum FGF21 level might be a result of its anti-inflammation effect responsive to systemic inflammation induced by generalized periodontitis." (PMID 36474191, 2022). "Longitudinal study or clinical controlled trials investigating FGF21 before and after periodontal treatment might clarify the role of periodontitis to FGF21." (PMID 36474191, 2022). "Recently, there have been few attempts determining the level of FGF21 in periodontitis patients." (PMID 36474191, 2022). "In periodontitis, the underlying immunoinflammatory dysregulation shows a decrease in the capacity of normalizing glycemia, as shown by an inverse relation to FGF-19 and FGF-21." (PMID 31998807, 2020). "First, the outcomes from this cross-sectional study could not be explained in causal-effect direction between FGF21 and periodontitis in MetS patients." (PMID 36474191, 2022). "Therefore, it was possible that the altered expression of serum FGF21 might be also modified by the systemic inflammation induced by generalized periodontitis apart from metabolic abnormalities." (PMID 36474191, 2022). "Therefore, the present study aimed to investigate the level of serum FGF21 in MetS patients with or without generalized periodontitis and the association of FGF21 to metabolic and periodontal parameters." (PMID 36474191, 2022). "Therefore, FGF21 might be a potential biomarker for linking Mets to periodontitis." (PMID 36474191, 2022). "Up to date, there are no studies investigating the level of circulating FGF21 in patients with MetS and periodontitis." (PMID 36474191, 2022). "Although the present study was not able to fully answer the relationship between FGF21 and periodontitis, the data elucidates the significant effect of periodontal disease on systemic health, especially MetS." (PMID 36474191, 2022). "Lastly, the biomarkers such as TNF-α and IL-1β, which are targeted by FGF21 and involved in periodontitis development, were not determined in the present study." (PMID 36474191, 2022). "One study showed the higher level of FGF21 in gingiva crevicular fluid (GCF) was collected from diabetic patients combined with periodontitis than those without periodontitis." (PMID 36474191, 2022).
peripheral arterial disease (2 papers, 2016 to 2021). A disorder of the arteries supplying the upper and lower extremity and the visceral organs. "FGF21 was also associated with femoral intima-media thickness and peripheral arterial disease in Chinese women but not in men." (PMID 33996935, 2021).
peripheral nerve injury (2 papers, 2021 to 2024). Injury to a peripheral nerve. "FGF-21 can inhibit the excessive activation of oxidative stress and autophagy-induced cell death, which is beneficial to myelin re-formation and nerve regeneration after peripheral nerve injury." (PMID 38606083, 2024). "Moreover, we previously revealed that a reduction in peripheral nerve injury (PNI)-induced oxidative damage could be achieved through fibroblast growth factor 21 (FGF21)-mediated Nrf2 signaling activation." (PMID 33479232, 2021).
prion disease (2 papers, 2020 to 2021). A transmissible disease that is caused by a protein that is able to induce abnormal folding of normal cellular proteins, leading to characteristic spongiform brain changes, which are associated with neuronal loss without an inflammatory response. "The induction of neuron-derived FGF21 has also been detected in brains of mouse models of tauopathy and prion disease." (PMID 32059608, 2020). "Based on this and other findings that show Fgf21 induction in mouse models of frontotemporal dementia (FTD) and prion disease, Fgf21 may be a suitable marker for neurodegenerative diseases that are accompanied by mitochondrial dysfunction." (PMID 34114603, 2021).
protein deficiency (2 papers, 2021 to 2025). "It is conceivable that a similar resistance develops in the context of chronic protein deficiency, where persistently elevated FGF21 fails to restore protein homeostasis." (PMID 40390366, 2025).
pterygium (2 papers, 2020 to 2024). A wedge-shaped fibrovascular lesion arising from the bulbar conjunctiva and extending to the cornea. "In the current study, the reduced level of FGF21 in patients with pterygium was associated with impaired lipid metabolism." (PMID 32095207, 2020). "The serum FGF21 levels were 319.09 ± 246.93 pg/ml and 608.88 ± 449.81 pg/ml (P = 0.005) in the pterygium group and control subjects, respectively." (PMID 32095207, 2020). "The serum FGF21 was significantly lower in patients with pterygium compared to non-pterygium patients (P = 0.005)." (PMID 32095207, 2020). "Our study showed that FGF21 levels were lower in patients with pterygium than the control subjects to a statistically significant level." (PMID 32095207, 2020). "The average serum FGF21 was 281.55 ± 40.74 pg/ml in males and 361.375 ± 10.298 pg/ml in females in the pterygium group." (PMID 32095207, 2020). "Our findings showed a significant difference in serum FGF21 between the pterygium and control groups." (PMID 32095207, 2020). "In conclusion, our findings suggest that low serum FGF21 in patients with pterygium affects the condition and may be a protective factor." (PMID 32095207, 2020). "In this study, the serum FGF21 is compared in patients with and without pterygium." (PMID 32095207, 2020). "Regarding the comparison of serum FGF21 in patients with and without pterygium, the results of the Mann–Whitney test showed a statistically significant difference in the mean of the serum FGF21 between the pterygium (319.09 ± 246.93) and control (608.88 ± 449.81) groups (P = 0.005)." (PMID 32095207, 2020).
pulmonary fibrosis (2 papers, 2022 to 2023). Chronic progressive interstitial lung disorder characterized by the replacement of the lung tissue by connective tissue, leading to progressive dyspnea, respiratory failure, or right heart failure. "Fresh evidence supported that FGF21 weakens pulmonary fibrosis by alleviating oxidative stress in vivo and in vitro." (PMID 35677107, 2022). "In a recent study, researchers observe that FGF21 inhibits pulmonary fibrosis by activating the Nrf-2 pathway, hence inhibiting ECM accumulation, and finally holding back fibrogenesis in pulmonary tissue." (PMID 35677107, 2022). "These may become the research directions of the mechanism of FGF21 in pulmonary fibrosis in the future." (PMID 35677107, 2022). "Exogenous FGF21 has been observed to inhibit pulmonary fibrosis." (PMID 35677107, 2022). "All in all, FGF21's anti-inflammatory, reducing oxidative stress, and inhibiting EMT mechanism in pulmonary fibrosis have been unearthed by diligent researchers." (PMID 35677107, 2022).
renal carcinoma (2 papers, 2016 to 2017). A carcinoma arising from the epithelium of the renal parenchyma or the renal pelvis. "More recently, the possibility of using FGF-21 as a prognostic or diagnostic cancer marker has been raised and evaluated for renal cancer, with promising results." (PMID 28522899, 2017). "We also measured circulating FGF21 levels in patients with other types of renal cancer." (PMID 27358750, 2016). "There is no information available on the role of FGF21 in tumor initiation and progression; further studies are needed to elucidate the mechanisms behind the increased serum FGF21 levels in renal cancer patients." (PMID 27358750, 2016).
Right ventricular hypertrophy (2 papers, 2022 to 2023). In this case the right ventricle is more muscular than normal, causing a characteristic boot-shaped (coeur-en-sabot) appearance as seen on anterior- posterior chest x-rays. "Hypoxia leads to upregulation of miR-27b in HPAECs, inhibits the expression of PPARγ and induces the secretion of IL-6, while fibroblast growth factor 21 (FGF21) can reduce the expression of IL-6 by inhibiting miR-27b, thus alleviating PH and right ventricular hypertrophy (RVH)." (PMID 37449201, 2023). "Exogenous administration of FGF21 relieved PH and right ventricular hypertrophy." (PMID 35437883, 2022).
Sleep apnea (2 papers, 2017 to 2020). An intermittent cessation of airflow at the mouth and nose during sleep is known as sleep apnea. "Indeed, our preliminary data showed that sleep-disordered breathing, an important mediator for accelerating oxidative stress and chronic inflammation, is associated with circulating FGF21 levels." (PMID 28582462, 2017). "The finding that FFA released from adipose tissue mediates hypoxia-induced FGF21 expression may explain the circadian rhythm of FFAs and FGF21 in patients with sleep apnea." (PMID 32922298, 2020). "Thus, the hypoxia status caused by severe sleep apnea after sleep onset results in an increase of circulating FFA, which may contribute to the nocturnal rise in FGF21." (PMID 32922298, 2020). "Therefore, interventional treatment of sleep-disordered breathing, such as continuous positive airway pressure, may be a promising way of reducing circulating FGF21 levels." (PMID 28582462, 2017).
tauopathy (2 papers, 2016 to 2020). Neurodegenerative disorders involving deposition of abnormal tau protein isoforms (tau proteins) in neurons and glial cells in the brain. "To pursue this issue, we fed ApoE−/− mice caloric-restricted for a long-term to raise hepatic as well as neuronal Fgf21 with the aim to prevent tauopathy via the AMPK/mTOR pathway and to improve cognitive performance." (PMID 27902456, 2016). "Further experiments are necessary to evaluate Fgf21 as a therapeutic tool to treat tauopathy for improvement of cognitive performance." (PMID 27902456, 2016).
thrombosis (2 papers, 2017 to 2022). "To test this hypothesis, we analyzed an animal model of thrombosis and found that FGF-21 suppresses thrombus formation and conveys little risk of bleeding." (PMID 35013379, 2022).
Ventricular arrhythmia (2 papers, 2021 to 2023). "In conclusion, FGF21 can improve MI and ventricular arrhythmia post MI by regulating the inflammation, fibrosis, and action potential duration of myocytes." (PMID 36594101, 2023). "We investigated that the onset of the first ventricular arrhythmias (arrhythmia in incubation period) was delayed by FGF21 compared to the rhbFGF21-untreated group in the ouabain model." (PMID 34630093, 2021). "Moreover, the onset of the first ventricular arrhythmias was delayed and the numbers of VF and maintenance were attenuated by FGF21 compared to the rhbFGF21-untreated group in the ouabain model." (PMID 34630093, 2021).
viral hepatitis (2 papers, 2013 to 2024). An acute or chronic inflammation of the liver parenchyma caused by viruses. "We plan to investigate whether circulating FGF21 levels tend to be higher in patients with hepatitis C compared to other viral hepatitis cases." (PMID 39211324, 2024).
acne (1 paper, 2022). An inflammatory process of the sebaceous glands which is characterized by comedones, nodules, papules and/or pustules on the skin. "Although early studies have shown that FGF21 can regulate inflammation in some diseases, its ability to suppress C. acnes-induced inflammatory responses during the development of acne remains unknown." (PMID 35408949, 2022). "Taken together, these findings indicate that FGF21 suppresses C. acnes-induced inflammation and might be used clinically in the management and treatment of acne." (PMID 35408949, 2022). "These anti-inflammatory properties of FGF21 suggest a possible mechanism in acne." (PMID 35408949, 2022). "Taken together, these findings confirm that FGF21 has the anti-inflammatory activities in this model and may prevent pathological changes and mitigate disease development in patients with acne." (PMID 35408949, 2022). "Other cells may also be involved in the pathogenesis of acne and in the effects of FGF21." (PMID 35408949, 2022).
acquired lipodystrophy (1 paper, 2021). An instance of lipodystrophy (disease) that is acquired during the lifetime of the individual. "An FGF21 disturbance may cause, i.a., acquired lipodystrophy." (PMID 34684585, 2021).
acute liver failure (1 paper, 2015). Rapid deterioration of liver function causing encephalopathy and coagulopathy. "Replenishment of FGF21 protects acute liver failure from acetaminophen-inducted hepatic ROS accumulation and reverses the abolishment of antioxidant gene expression by increasing PGC1α." (PMID 25991671, 2015).
alcohol withdrawal syndrome (1 paper, 2024). "Previous studies showed that BDNF played a significant role in the processes of alcohol withdrawal syndrome, and FGF21 is related to AUD." (PMID 38721616, 2024).
alcohol-related disorders (1 paper, 2021). Disorders related to or resulting from abuse or mis-use of alcohol. "Recent studies suggest that FGF19, FGF21, and FGF23 are associated with alcohol and alcohol-related disorders." (PMID 34490035, 2021). "Members of fibroblast growth factor (FGF) 19 superfamily, including FGF19, FGF21, and FGF23, are major endocrine mediators that play an important role in alcohol metabolism and alcohol related disorders." (PMID 34490035, 2021).
allergic disease (1 paper, 2020). An immune response that occurs following re-exposure to an innocuous antigen, and that requires the presence of existing antibodies against that antigen. "Our results indicated that lower proportions of NKT due to EGF and FGF21 supplementation at the end of the suckling period may be beneficial in the prevention of allergic diseases, which are highly prevalent during these stages of life." (PMID 32599899, 2020).
amyotrophic lateral sclerosis (1 paper, 2023). Amyotrophic lateral sclerosis (ALS) is a neurodegenerative disease characterized by progressive muscular paralysis reflecting degeneration of motor neurons in the primary motor cortex, corticospinal tracts, brainstem and spinal cord. "Moreover, in an amyotrophic lateral sclerosis (ALS) model, the activation of the FGF21 signaling pathway slowed the onset of ALS by regulating the exercise capacity, metabolic status, and inflammation levels of mice." (PMID 38069273, 2023).
ankylosing spondylitis (1 paper, 2024). An autoimmune chronic inflammatory disorder characterized by inflammation in the vertebral joints of the spine and sacroiliac joints.
Ataxia (1 paper, 2023). Ataxia refers to impaired coordination of voluntary muscle movement. "Conversely, pharmacologic FGF21 administration reduces the time needed for mice to recover from ethanol-induced unconsciousness and ataxia." (PMID 36889282, 2023).
Barth syndrome (1 paper, 2026). Barth syndrome (BTHS) is an inborn error of phospholipid metabolism characterized by dilated cardiomyopathy (DCM), skeletal myopathy, neutropenia, growth delay and organic aciduria. "These adaptations probably contribute to the altered metabolic phenotype observed in Barth syndrome and highlight a potential role for hormones and circulating factors such as FGF-21 in maintaining islet function and glucose homeostasis." (PMID 41136741, 2026).
Candida infections (1 paper, 2024). "Supportive evidence that low FGF-21 concentrations are deleterious for patients suffering from Candida infections comes from a study showing an upregulation of FGF-21 concentrations in patients with chronic mucocutaneous candidiasis after successful treatment with a JAK inhibitor." (PMID 39330398, 2024).
channelopathies (1 paper, 2022). "The level of FGF-21 was one of surrogate markers that are parallel to the severity of hypoxia, inflammation, and oxidative stress on mitochondria but was not the validated method to estimate the hemodynamic change of the glomerulus or channelopathies of podocytes or renal tubular cells." (PMID 35528011, 2022).
cholelithiasis (1 paper, 2022). The presence of crystallized deposits forming in the gallbladder or biliary tree, primarily composed of cholesterol, bilirubin, and bile. "Higher levels of chemerin, retinol-binding protein 4 (RBP-4), and fibroblast growth factor 21 (FGF-21) have been observed in children with cholelithiasis." (PMID 36362164, 2022).
Cockayne syndrome (1 paper, 2025). A multisystem condition characterized by short stature, a characteristic facial appearance, premature aging, photosensitivity, progressive neurological dysfunction, and intellectual deficit. "It is established that complex I dysfunction within the liver seen in e.g., Cockayne syndrome, gives rise to high concentrations of circulating GDF15 and FGF21 resulting in suppressed food intake, which is reversed by blocking GDF15 alone." (PMID 40562759, 2025).
congenital cardiomyopathy (1 paper, 2025). "Under normal conditions, FGF21 loss had minimal effects on most cardiac FAO genes, except peroxisomal Ehhadh, Hsd17b4, and ER-residing Hacd1/2 (linked to congenital cardiomyopathy)." (PMID 40998786, 2025).
coronary artery calcification (1 paper, 2023). Calcification of the coronary artery, used as a measure of coronary atherosclerosis, a risk factor for myocardial infarction. "Another study stratified 1132 DM patients with coronary artery calcification based on their FGF21 levels and recorded their major adverse cardiovascular events during 1.5-5.1 years of follow-up." (PMID 36594101, 2023). "In DM patients with coronary artery calcification, a lower level of FGF21 predicts a better long-term prognosis." (PMID 36594101, 2023).
cyst (1 paper, 2013). A sac-like closed membranous structure that may be empty or contain fluid or amorphous material. "FGF21 expression was also high in hepatic tissues (right of the black broken line) adjacent to the wall of liver cysts, but not the cells in cyst lesions (left of the black broken line)." (PMID 23590285, 2013).
demyelination (1 paper, 2020). "Previous study showed that peripherally derived FGF-21 leaked into the injured brain and facilitate remyelination in a mouse model of lysophosphatidylcholine-induced demyelination." (PMID 31900170, 2020).
dependence (1 paper, 2022). "Further, naloxone-precipitated physical dependence behavior, (i.e., number of vertical jumps post-naloxone injection) is depressed in FGF21-Tg mice compared to wildtype littermates, suggesting that acute morphine physical dependence is regulated by FGF21 activity." (PMID 36532632, 2022).
diabetic foot ulcers (1 paper, 2021). "FGF1, FGF2, FGF4, FGF7, FGF16, FGF21, and FGF23 have been found to have good therapeutic outcomes for diabetic foot ulcers." (PMID 34831463, 2021).